ABITRAM (actin binding transcription modulator)
Description:
Actin-binding protein that regulates actin polymerization, filopodia dynamics and increases the branching of proximal dendrites of developing neurons.
Synonyms: C9orf6; FAM206A; CG-8; FLJ20457; Simiate
Tractability: PROTAC: ubiquitination databases record sites on it.
Gene: Protein-coding gene on chromosome 9 (108,934,400 to 108,950,744, forward strand). Ensembl gene ENSG00000119328.
Subcellular location: Nucleus speckle; Cell projection, lamellipodium; Nucleus; Cell projection, growth cone; Cell projection, dendrite
Subcellular location (Human Protein Atlas): Cytosol; Nucleoplasm; Cytokinetic bridge; Kinetochore; Mitotic spindle; Primary cilium; Primary cilium tip
Gene Ontology:
Molecular function: protein binding; actin filament binding; actin monomer binding
Biological process: dendrite morphogenesis; regulation of actin filament polymerization; regulation of filopodium assembly
Cellular component: dendrite; filopodium tip; growth cone; lamellipodium; nuclear speck; nucleus
Genetic constraint (gnomAD): Loss-of-function variants: 15 observed, 19.66 expected, observed/expected ratio (o/e) 0.76, 90% interval 0.51 to 1.17. The upper end of that interval is the gene's LOEUF score, 1.17, which puts it in group 5 of 6, group 1 being the genes least tolerant of losing a copy. Missense variants: 198 observed, 205.52 expected, observed/expected ratio (o/e) 0.96, 90% interval 0.86 to 1.08. Synonymous variants: 65 observed, 69.83 expected, observed/expected ratio (o/e) 0.93, 90% interval 0.76 to 1.14.
Homologues: Orthologues: chimpanzee ABITRAM (99% identical), macaque ABITRAM (99% identical), rabbit ABITRAM (92% identical), guinea pig ABITRAM (92% identical), rat Abitram (88% identical), dog ABITRAM (87% identical), mouse Abitram (86% identical), tropical clawed frog abitram (72% identical), zebrafish abitram (68% identical), Drosophila melanogaster CG9288 (41% identical), Caenorhabditis elegans F54F2.7 (23% identical).